ANXA1 (annexin A1)
Diseases named in the same sentence as ANXA1 in open-access papers (continued):
Sharing a sentence is not in itself a finding about the gene and the disease.
tumor (continued). "In brief, we uncovered an unanticipated ablation of the Notch1‐p15‐mediated tumor suppression by ANXA1 in AML through the ubiquitination‐proteasome degradation of NICD to block the transcriptional activation of p15 in vitro and in vivo." (PMID 39447086, 2024). "This tumour type is well-documented as expressing high levels of ANXA1 which correlates with poorer survival." (PMID 38200229, 2024). "The identification cohort showed the overexpression of IGFBP7 and ANXA1 regarding all tumor stages versus controls, in exosomes isolated from serum." (PMID 38893148, 2024). "Annexin A1 showed strong staining of the tumor tissue, especially in the keratinized part of the carcinoma." (PMID 38893148, 2024). "LSCC showed strong ANXA1 expression in the whole tumor tissue, especially in the keratinized part of the carcinoma." (PMID 38893148, 2024). "By characterizing dynamics in stem-cell crosstalk with the microenvironment along the pseudotime axis, we found differential roles of ANXA1 at different stages of tumor development." (PMID 38645221, 2024). "Mechanistically, ANXA1 directly bound to the intracellular domain of Notch1 (NICD) to target this tumor suppressor for degradation." (PMID 39447086, 2024). "In contrast, the central memory T cell (Tcm) cluster was represented by cells expressing TCF7, ANXA1, LEF1, and SELL genes and is commonly associated with central memory and tumor inhibition function." (PMID 37615858, 2024). "In the 2004 group from California, USA, they obtained positive results after administration of monoclonal ANXA1 antibodies combined with radiotherapy against a rat tumor model." (PMID 38892394, 2024). "These cytokines, commonly present in the tumor microenvironment, activate specific signaling pathways that promote ANXA1 expression." (PMID 37507468, 2023). "We compared the transcriptome data between normal samples and GBM tumor samples, which indicated that ANXA1, PDPN, COL6A1, BCL3, RUNX1, and WWTR1 were upregulated and compared to normal samples, BCL11A was downregulated in GBM tumor samples." (PMID 37434432, 2023). "Proteomics technology has revealed that ANXA1 mainly regulates the processes related to tumour cell skeletal remodelling and immune responses, thus affecting the invasive migration of cancer cells." (PMID 36936694, 2023). "External cohort of 95 GBM patients by immunohistochemistry (IHC) assay demonstrated that ANXA1, COL6A1, and PDPN were significantly upregulated in tumor tissues of high‐risk GBM patients." (PMID 37434432, 2023). "Tumor-secreted ANXA1 drives microglial migration, while microglia-secreted ANXA1 promotes microglial activation and regulates the expression of inflammatory factors." (PMID 38104104, 2023). "A growing body of evidence supports the notion that dysregulations in Anxa1 expression play a critical role in the pathogenesis of cancer, encompassing tumor development, invasion, metastasis, initiation, and acquired resistance to therapies." (PMID 37950728, 2023). "The up-expression of AnxA1 by tumor cells takes place in solid tumors of different origins and is associated with poor outcomes, implicating AnxA1 as a common mediator of cancer development." (PMID 36766767, 2023). "The benign hyperkeratosis specimens displayed nuclear, cytoplasmic and membranous staining for Annexin-A1 in the suprabasal epithelial cells." (PMID 37954869, 2023). "In parallel, it will also be highly informative to learn more about the fate and dynamics of ANXA1-expressing cells and their relative contributions to mammary gland development and homeostasis, but also to tumour formation and heterogeneity." (PMID 36631478, 2023). "ANXA1 is an endogenous immunomodulatory protein that plays a role in tumor development, including cell proliferation, apoptosis, metastasis, and invasion." (PMID 38102661, 2023).
tumor (continued). "Several studies have indicated that the seven key prognostic genes identified in this study for UCEC, including TSPYL5, VNN2, ANXA1, and DCAF12L1, are associated with tumor occurrence and development." (PMID 37363398, 2023). "A broader role for annexin A1 beyond inflammation has been reported, including in tumor cell proliferation, differentiation, apoptosis, invasion, angiogenesis, and metastasis." (PMID 37056569, 2023). "This resulted in a low proliferative rate and low INFγ production of CD8+ lymphocytes co-cultured in vitro with ANXA1+ tumor M2 macrophages, as well as in increased tumor mass in orthotopic mouse xenografts." (PMID 36835628, 2023). "Among the genes differentially expressed, ANXA1 has been revealed to have a pivotal role in recruiting monocytes at tumor sites and inducing their differentiation into M2-like macrophages, which are typically immunosuppressive." (PMID 36835628, 2023). "We found that several DAMP-related genes, including Hmgb1, Calr, and Anxa1, were significantly overexpressed in Ero1aKO tumor cells compared with WT controls, suggesting the intracellular danger signaling pathways that govern ICD in Ero1aKO tumors." (PMID 37769655, 2023). "Of particular interest, ANXA1 plays dual roles with regard to invasion and metastasis among different tumour cells." (PMID 36936694, 2023). "A noted feature of the HPV-OPSCC specimens was few clusters of matured and differentiated nonbasaloid cells that showed prominent nuclear and cytoplasmic Annexin-A1 staining while the remainder of the tumor mass was devoid of staining." (PMID 37954869, 2023). "Lung melanoma metastatic mice (C57BL/6; i.v. injected B16F10 cells) showed neutrophilia, elevated AnxA1 serum levels, and higher labeling for AnxA1 in neutrophils than in tumor cells at the lungs with metastasis." (PMID 36766767, 2023). "Up-regulation of ANXA1 was also reported with a role in a variety of tumor development processes and metastasis-free survival in high-grade compared to low-grade UBC." (PMID 37501157, 2023). "Immunofluorescence and subcellular fractionation revealed Annexin A1, A2, and A5 in the cytoplasm and nuclei of tumor cells." (PMID 37117324, 2023). "ANXA1 is a 37 kDa calcium- and phospholipid-binding protein that participates in carcinogenesis and tumor progression due to its ability to modulate various cancer-related pathways." (PMID 35406748, 2022). "ANXA1 expression level distributions plot, in a pan‐cancer analysis by TIMER, showed that ANXA1 was obviously elevated in a variety of tumours, including GBM, compared with ANXA1 expression in normal groups." (PMID 35770335, 2022). "To assess the effect of tumor intrinsic ANXA1 in an in vivo system, we utilized a model of brain metastasis via intra-carotid injection of 4T1-12B (luciferase expressing) cells." (PMID 35382852, 2022). "Numerous investigations have revealed that ANXA1 is involved in tumor proliferation, invasion, migration and EMT in vitro and in vivo." (PMID 34991599, 2022). "In the cell subsets of normal samples, FN1 and ANXA1 were high expressed in tumor cells and low expressed in myeloid cell and fibroblast; CLU was low expressed in tumor cells and high expressed in myeloid cell and fibroblast." (PMID 35359404, 2022). "ANXA1 transfer resulted in the promotion of proliferation, invasion, and epithelial-to-mesenchymal transition of Nthy-ori 3-1 cells, as well as tumor growth, in a xenograft mouse model." (PMID 35406748, 2022). "ANXA1 is known as an anti-inflammatory protein but is recognized to have a broader role in tumour cell biology beyond inflammation alone." (PMID 39290334, 2022). "In PC, the protein ANXA1 has been identified as an oncogenic factor acting in an autocrine/paracrine way, and also as a component of tumor-deriving extracellular vesicles." (PMID 36230687, 2022). "The functional role of ANXA1 in the tumor microenvironment should also be further validated by the use of neutralizing antibodies against ANXA1." (PMID 35382852, 2022).
tumor (continued). "Disease models with better clinical relevance such as mammosphere culture and mouse tumor xenografts should be used to interrogate the targetability of AnxA1 in highly heterogenous TNBC." (PMID 35897832, 2022). "The opposite expression levels of ANXA1 in different tumor types makes difficult to understand precisely the role played by ANXA1 during tumorigenesis." (PMID 36247003, 2022). "Cell apoptosis was enhanced in ANXA1 knockdown/bortezomib combination groups compared to that in ANXA1 knockdown alone or bortezomib‐treated alone cells, supporting a pro‐tumour role for ANXA1 in this disease." (PMID 35146757, 2022). "To investigate the mechanism by which ANXA1 regulates tumour immunity, we analysed the relationship between ANXA1 and immune molecules." (PMID 35770335, 2022). "Our current study further demonstrated that silencing ANXA1 slows tumor growth and reverses the effects of stress on the changes in the gut microbiome and fatty acid metabolism." (PMID 35664067, 2022). "ANXA1 has been studied in many tumours in the past 20 years, with a variety of biological functions." (PMID 35415239, 2022). "Studies investigating the role of ANXA1 in tumour progression demonstrated that knocking out ANXA1 resulted in reduced tumour growth, angiogenesis and metastasis." (PMID 35146757, 2022). "An increasing number of studies have shown the expression and function of AnxA1 in tumours to be tissue- and tumour-specific." (PMID 36123610, 2022). "We compared the parental 4T1 and ΔANXA1 4T1 to examine the effect of tumor intrinsic ANXA1 in brain metastasis." (PMID 35382852, 2022). "As expected, the results indicated that the tumor volume and weight of the ANXA1 knockdown group were significantly smaller than those of the control group." (PMID 34991599, 2022). "We found that in adjacent non-tumor breast tissues, both AnxA1 and IL-6 were expressed in glandular and in the myoepithelial cell layer." (PMID 35626741, 2022). "ANXA1 is specifically expressed in tumours, which makes it an important biological indicator for early tumour diagnosis and prognosis." (PMID 35415239, 2022). "IHC staining showed that P-EGFR and Ki-67 expression significantly decreased in tumor tissues of the ANXA1 knockdown group." (PMID 34991599, 2022). "In this regard, high ANXA1 expression levels have been found in PC inducing the acquisition of an aggressive phenotype from both tumor and stromal cells." (PMID 36230687, 2022). "ANXA1 expression in HNSCC was closely related with the tumor differentiation and therefore it emerged as a differentiation marker potentially applicable for histopathological grading." (PMID 36247003, 2022). "AnxA1 can steer the macrophage polarization toward the M2 phenotype to create a pro-tumor immune environment." (PMID 35897832, 2022). "Like its expression patterns, the role of ANXA1 has been found to be inconsistent among tumor initiation, progression, and metastasis where it has been shown to be not only a tumor suppressor but also a tumor promotor." (PMID 33959206, 2021). "In this way, Annexin A1 inhibits the anti-tumor immunity and supports the formation of an immunosuppressed tumor microenvironment that promotes tumor growth and metastasis." (PMID 34571894, 2021). "A significantly decreased tumor volume was observed in the group of mice treated with ANXA1 siRNA and Osimertinib." (PMID 34439260, 2021). "With continuous more in-depth research in this field, ANXA1 has been revealed to play regulatory roles in a variety of cellular processes during tumor progression." (PMID 33531975, 2021). "We previously reported that IF7 peptide, which binds to the annexin A1 (ANXA1) N-terminus, functions as a tumor vasculature-targeted drug delivery vehicle after intravenous injection." (PMID 33406123, 2021). "Several studies, including one using ANXA1 knockout mice, showed that stroma-derived ANXA1 expression promotes tumor growth, angiogenesis, and metastasis." (PMID 33804148, 2021).
tumor (continued). "We measured the immunohistochemical score for each PTC patient and the results showed that the average scores of ANXA1 staining were much higher in tumor areas than neighboring normal thyroid regions." (PMID 33531975, 2021). "At a single-cell level, we found that ANXA1 is highly expressed in M2 macrophages and tumor cells of the mesenchymal subtype." (PMID 34912807, 2021). "AnxA1 has attracted much attention due to its pleiotropic functions and its involvement in tumor growth and progression." (PMID 34571894, 2021). "Alternatively, the development of a doxorubicin-DNA aptamer conjugate that specifically recognizes AnxA1 on the surface of cancer cells significantly enhanced targeted therapy against tumours in vivo." (PMID 33810523, 2021). "Here, we report BNCT efficacy after rapid, ultralow-dose administration of either tumor vasculature-specific annexin A1-targeting IFLLWQR (IF7)-conjugated 10BPA or borocaptate sodium (10BSH)." (PMID 33446132, 2021). "We administered IF7 conjugated to fluorescent Alexa 488 to tumor-bearing mice and demonstrated excellent targeting to Anxa1 within minutes of injection." (PMID 33446132, 2021). "For example, Annexin A1 released from tumor cells was shown recently to activate Fpr2 on the surface of regulatory T cells to enhance their immunosuppressive function." (PMID 33800279, 2021). "Strong evidence underlines the role of ANXA1 in epithelial-mesenchymal transition (EMT) and alternative macrophage polarization, pivotal in tumor invasion and metastasis." (PMID 34200100, 2021). "Herein, we provide the first evidence that ANXA1 is a positive regulator of tumor growth and metastasis in PTC, complementing its biological function via influencing the dynamic properties of EMT and regulating IL-6/JAK2/STAT3 signaling network." (PMID 33531975, 2021). "Anxa1 is reportedly present on the surface of tumor endothelial cells in several tumor types in mice and humans and has been proposed to be a valid target for the tumor vasculature." (PMID 33446132, 2021). "Remarkably, Annexin A1 shows pro-invasive and pro-tumoral properties in several cancers either by eliciting autocrine signaling in cancer cells or by inducing a favorable tumor microenvironment." (PMID 34571894, 2021). "Patients with larger tumor size often exhibited the elevated level of ANXA1 in comparison with those with smaller tumor size." (PMID 33531975, 2021). "According to the GEPIA database, the results of differential expression analysis revealed an increased expression of ANXA1 in the tumor samples compared with normal samples in LGG samples and GBM samples." (PMID 34422796, 2021). "Collectively, our data demonstrate a novel cell-autonomous role for Annexin A1 in the promotion of tumor-forming capacity in certain TNBC tumors." (PMID 33800279, 2021). "In contrast, ANXA1 absence mitigated tumor 4T1 tumor growth and metastasis in vivo by promoting M1 macrophage polarization." (PMID 34207035, 2021). "ANXA1-silenced tumor cells showed a dramatic reduction of Ki-67 staining compared to control cells, indicating in vivo tumor cell proliferation was robustly hindered by silencing of ANXA1." (PMID 33531975, 2021). "Accordingly, 48% of cases displayed high Annexin A1 expression in cell membranes of tumor cells while others showed weak or negligible staining." (PMID 34943928, 2021). "Single cell tracking profiles extrapolated by OOC system displayed that FPR1 expressed by immune cells, particularly dendritic cells (DCs), is required to “sense” Anxa1 emanated from dying tumor cells and to migrate toward them engaging in stable interactions." (PMID 33842539, 2021). "In our study, we further showed the successful knockdown of ANXA1 using Accell siRNA in the tumor xenograft animal model." (PMID 34439260, 2021). "Expression of several genes identified by usare known predictors of clinical outcome in different tumor types including ANXA1, FOXJ3 and CDC25 (Liuet al., 2019, 2020), among manyothers." (PMID 34617951, 2021).
tumor (continued). "Here, we have studied the role of this compound as interfering with endothelial cells activation in response to the paracrine effects of annexin A1 (ANXA1), known to be involved in promoting tumor progression." (PMID 34944403, 2021). "In other tumors, e.g., breast and epithelial ovarian cancer, clinical studies have observed a similar link between ANXA1 overexpression and longer overall survival, which was correlated to inhibition of tumor cells metastasis." (PMID 33959206, 2021). "In this scenario, the protein Annexin A1 (ANXA1) has been identified as a potential biomarker for tumor differentiation and prognosis, maintaining a tissue-specific role as an oncogene or oncosuppressor." (PMID 34944403, 2021). "AnxA1 then binds to FPR1 on dendritic cells, which phagocytose and kill malignant cells, but also present tumour-associated antigens, which are then recognized and eliminated by cytotoxic T lymphocytes." (PMID 33810523, 2021). "ANXA1 was a kind of annexin in exosomes released by activated MSCs, which was regarded as an anti-inflammatory molecule, while the tumor-induced inflammatory molecules would promote the tumor growth and metastasis." (PMID 33922480, 2021). "They showed that exosomes containing EGFR are formed thanks to the activity of AnxA1, inducing tumor specific Tregs." (PMID 34571894, 2021). "For example, cell surface Anxa1 stimulates formyl-peptide receptor 1 (FPR1), which is implicated in anti-tumor immune responses elicited by anthracyclines or oxaliplatin." (PMID 33446132, 2021). "Annexin A1 is a key functional player in tumor development, linking the various components in the tumor stroma by its actions in endothelial cells and immune cells." (PMID 34484309, 2021). "The administration of cyclosporine H, an FPR1 antagonist, abolishes the antitumor effect of chemotherapy, suggesting that FPR1 expression in the host and annexin A1 expression in tumor cells are required for the chemotherapeutic inhibition of tumor growth." (PMID 34638242, 2021). "We found that LGALS9_CD44, MIF_TNFRSF14, CD47_SIRPG, MDK_LRP1 and LGALS9_HAVCR2, CD74_COPA, C3_C3AR1, ANXA1_FPR3 interactions were upregulated in both ductal-tumor and malignant cells versus ductal-normal." (PMID 35087839, 2021). "In particular, the expression of ANXA1 was found to increase with the progression of tumor grade and malignancy." (PMID 34422796, 2021). "We further analyzed the expression profiles of ANXA1 in our cohort consisting of 64 PTC patients, RT-PCR results demonstrated that ANXA1 was prominently upregulated in PTC specimens compared to matched adjacent non-tumor tissues." (PMID 33531975, 2021). "We also noted that some proliferation-associated genes in tumor cells were also significantly regulated by CRNDE knockdown, including IGFBP4, ANXA1, KLF6, AATF, and IFI16." (PMID 33298855, 2020). "AnxA1 is known to play a role in tumor cell proliferation and has been shown to be involved in metastatic behavior in cancer cells, including invasion, migration, and epithelial-mesenchymal transition." (PMID 32497150, 2020). "Remarkably, none of the commercially available antibodies evaluated were found to meet the criteria of the binding capability to characterize the tumor vascular anxA1 in both human and mouse tissues." (PMID 32497150, 2020). "To identify rodent tumor models that are representative of the vascular anxA1 staining observed in human lung tumor specimens, we conducted IHC analysis of intratumoral vessels in multiple rodent models." (PMID 32497150, 2020). "We confirmed our previously reported result, the existence of the Anxa1 N-terminal domain on the surface of tumour vasculature surface in the mouse." (PMID 32921792, 2020). "Two rodent tumor models, B16-F10 and Py230, were determined to have upregulated anxA1 expression in the intratumoral vasculature." (PMID 32497150, 2020).